PALB2 (partner and localizer of BRCA2)
Diseases named in the same sentence as PALB2 in open-access papers (continued):
Sharing a sentence is not in itself a finding about the gene and the disease.
melanoma (13 papers, 2013 to 2024). A malignant, usually aggressive tumor composed of atypical, neoplastic melanocytes. "The implication of other candidate genes in melanoma predisposition is supported by less conclusive evidence, such as PALB2, in which a deleterious mutation has been detected in a single individual affected by four kinds of cancer, including melanoma." (PMID 26106605, 2015). "The PALB2/BRCA2 protein interaction, as well as the increased melanoma risk observed in families harbouring BRCA2 mutations, makes PALB2 a candidate for melanoma susceptibility." (PMID 24949998, 2014). "In our study we present an individual with two primary melanomas, bladder cancer, leukaemia and non-small cell lung cancer who is a carrier of the PALB2 p.Y1183X variant." (PMID 24949998, 2014). "This is the largest study reported to date to assess the relationship between germline PALB2 mutation and melanoma risk." (PMID 24949998, 2014). "Larger sample sizes will clearly be needed to better characterize the spectrum of cancers associated with deleterious PALB2 mutations along with a larger sample of melanoma-only families to unambiguously determine the role of PALB2 in melanoma susceptibility." (PMID 24949998, 2014). "Finally, we compare the frequency of mutations of the core HR genes BRCA1/2, CHEK2 and PALB2 in non-melanoma skin cancers." (PMID 34084283, 2021). "Given the small size of these studies, the association between PALB2 and melanoma risk remains unclear." (PMID 24949998, 2014). "Additionally, DNA methylation levels at the promoter regions of BAP1, MITF, and PALB2 genes were statistically associated with the number of melanomas presented by the individual and a hypermethylation of POT1 promoter was associated with Breslow thickness of the tumors." (PMID 26106605, 2015). "The germline variants of BRCA2, POLE, WRN, FANCI, PALB2, and RAD54B genes, involved in DNS repair mechanisms, have been implicated in rendering melanoma patients more susceptible to tumor progression and affecting their response to treatments." (PMID 39795882, 2024). "PALB2 protein partners with BRCA2 in homologous recombination, and mutations in PALB2 are similarly implicated in an increased melanoma risk and poorer survival." (PMID 39795882, 2024). "Additionally, variants of FANCI, PALB2, and RAD54B are associated with altered survival outcomes in melanoma patients." (PMID 39795882, 2024). "To assess the contribution of PALB2 to melanoma predisposition we sequenced the protein-coding region of PALB2 in probands from 201 melanoma families lacking pathogenic mutations in know melanoma susceptibility genes." (PMID 24949998, 2014). "A plausible candidate that might contribute to the melanoma risk landscape in certain individuals is partner and localizer of BRCA2 (PALB2)." (PMID 24949998, 2014). "Here, our aim was to investigate whether patients in the Hungarian melanoma cohort (n = 17) with increased risk carry any pathogenic or likely pathogenic germline variants of the BRCA2, POLE, WRN, FANCI, PALB2, and RAD54B genes associated with melanoma survival and response to therapy." (PMID 39795882, 2024). "Overall our data do not support a case for PALB2 being associated with melanoma predisposition." (PMID 24949998, 2014). "We therefore sought to determine the incidence of germline PALB2 mutations in a larger series of 201 CDKN2A and CDK4 mutation-negative melanoma families, including 63 with confirmed cases of breast, pancreatic, or multiple other types of cancer." (PMID 24949998, 2014).
pancreatic ductal adenocarcinoma (13 papers, 2018 to 2025). An infiltrating adenocarcinoma that arises from the epithelial cells of the pancreas. "For pancreatic ductal adenocarcinoma, platinum-treated patients who had PALB2 mutations had a higher overall survival (mean: 20.1 months) compared to non-mutated controls (mean: 15.5 months), (p = 0.002)." (PMID 37628606, 2023). "For the small subset of pancreatic ductal adenocarcinoma (PDAC) patients with loss-of-function mutations to BRCA1/2 or PALB2, both first-line and maintenance therapy differs significantly." (PMID 35205643, 2022). "Here we report a clinical case of a 56-year-old woman with pancreatic ductal adenocarcinoma harboring a somatic PALB2 mutation." (PMID 36119518, 2022). "Mutations in PALB2 genes increase the risk of pancreatic duct adenocarcinoma." (PMID 38730578, 2024). "Furthermore, in a Japanese study, two out of 54 patients with pancreatic ductal adenocarcinoma carried deleterious variants of PALB2 gene." (PMID 33718150, 2021). "For this purpose, we used conditional null alleles of Palb2 (Palb2flox2-3), Brca1 (Brca1flox2) and Brca2 (Brca2flox3-4) in combination with the well characterized Pdx1-Cre transgene that has been extensively used for modeling pancreatic ductal adenocarcinoma (PDAC) in mice." (PMID 31877165, 2019). "Approximately 4% of all patients with pancreatic ductal adenocarcinoma have an underlying gene defect, with ATM, BRCA1/2, and PALB2 being the most commonly affected genes." (PMID 30736435, 2019).
hereditary cancer syndromes (12 papers, 2017 to 2025). "This gene is a homologous recombination repair (HRR) gene family, and germline P/LP variants in the PALB2 are causes of a hereditary cancer syndrome." (PMID 40564049, 2025). "Regarding the PC group, three patients (representing 9.3% of the PC cohort and 50% of the PC patients with germline test done) were diagnosed with an inherited syndrome: two HBOC (1 BRCA2 and 1 PALB2) and one ATM hereditary cancer syndrome (ATM)." (PMID 32842532, 2020).
neuroblastoma (12 papers, 2013 to 2025). Neuroblastoma (NB) is the most common solid, extracranial childhood tumor. "Germline heterozygous mutations in BRCA1, BRCA2, and PALB2 were found in eight children with a spectrum of cancers including leukemia, CNS tumors, neuroblastoma, osteosarcoma, and rhabdomyosarcoma." (PMID 32962238, 2020). "Particularly, germline mutations in BRCA2 and PALB2, that PALB2 binds to the N terminus of BRCA2 and has a key role in localization and stabilization of BRCA2, have been detected that they were associated with the development of neuroblastoma." (PMID 28055978, 2017). "Although this child had undergone SOC germline molecular testing (karyotyping, copy number array, direct sequencing of neuroblastoma predisposition genes), PALB2 had not been interrogated as it is viewed as irrelevant in neuroblastoma predisposition investigations." (PMID 38956197, 2024). "Among the rare germ-line variants predisposing to neuroblastoma identified by the TARGET study, PALB2 contained two rare non-synonymous mutations in SH-SY5Y." (PMID 25528190, 2014).
Hereditary breast cancer (10 papers, 2019 to 2025). Breast carcinoma that has developed in relatives of patients with history of breast carcinoma. "The interaction between PALB2 and BRCA2 is important for maintaining genomic integrity.Moreover, BRCA2 and BRCA1 are the most common causes of hereditary breast cancer." (PMID 34092963, 2021). "Larger cohort studies are needed to further clarify the true contribution of CNVs in PALB2 and other non-BRCA genes to hereditary breast cancers." (PMID 40361347, 2025).
Peutz-Jeghers syndrome (9 papers, 2016 to 2025). An autosomal dominant disorder caused by pathogenic variants in the STK11 gene, characterized by hamartomatous polyps in the gastrointestinal tract, mucocutaneous pigmentation and increased risk of GI and extra-GI malignancies. "This includes pathogenic variants in cancer predisposition genes, e.g. BRCA2 and PALB2; Lynch Syndrome, Peutz-Jeghers Syndrome (PJS), Familial Atypical Multiple Mole Melanoma and Hereditary Pancreatitis." (PMID 31666883, 2019).
familial breast cancer (8 papers, 2007 to 2020). "Heterozygous germline PALB2 LOF mutations were previously shown to be associated with familial breast cancer with a prevalence of about 1%." (PMID 33193564, 2020). "PALB2 is an important BRCAx candidate for familial breast cancers (FBC)." (PMID 33193564, 2020).
metastatic prostate carcinoma (8 papers, 2019 to 2024). A carcinoma that arises from the prostate gland and has spread to other anatomic sites. "In metastatic prostate cancer, an expanded HRD panel included patients with mutations to BRCA1, BRCA2, ATM, FANCA, CHEK2, PALB2, NBN, or HDAC2." (PMID 35205643, 2022).
serous ovarian cancer (8 papers, 2013 to 2025). "We have found strong evidence that carriers of PALB2 deleterious mutations are at increased risk of high-grade serous ovarian cancer." (PMID 32546565, 2021). "The ORs associated for high-grade serous ovarian cancer were 3.01 for PALB2 (95% CI 1.59 to 5.68; p=0.00068), 1.99 for POLK (95% CI 1.15 to 3.43; p=0.014) and 4.07 for SLX4 (95% CI 1.34 to 12.4; p=0.013)." (PMID 32546565, 2021). "However, based on the Bayes false discovery probability, only the association for PALB2 in high-grade serous ovarian cancer is likely to represent a true positive." (PMID 32546565, 2021). "Approximately 50% of high-grade serous ovarian cancers are characterized by HR deficiency, which involves mutations in BRCA1/2, the MRN complex (MRE11, RAD50, NBS1), ATM, RAD51C/D, PALB2, BRIP1, BARD1, and other genes." (PMID 31572446, 2019). "We therefore sought to investigate the role of PALB2 methylation in high-grade serous ovarian cancers." (PMID 23587053, 2013). "The 92 high-grade serous ovarian cancer samples were investigated for aberrant PALB2 methylation in exon 1 using MS-HRM." (PMID 23587053, 2013). "PALB2 methylation was investigated in 92 high-grade serous ovarian cancer samples using methylation-sensitive high-resolution melting analysis." (PMID 23587053, 2013). "In conclusion, we showed that epigenetic silencing by DNA methylation is an unlikely mechanism for PALB2 inactivation in high-grade serous ovarian cancers." (PMID 23587053, 2013). "We sought to investigate aberrant PALB2 methylation in a large number of high-grade serous ovarian cancers using methylation-sensitive high-resolution melting (MS-HRM)." (PMID 23587053, 2013). "We also detected two PALB2 PGVs in individuals with high-grade serous ovarian cancer." (PMID 34113003, 2021). "However, because high-grade serous ovarian cancer is driven by disrupted homologous recombination, we may have reasonably expected to observe PALB2 methylation as a method of pathway disruption." (PMID 23587053, 2013). "Epigenetic silencing by DNA methylation of PALB2 is not a common event in high-grade serous ovarian cancers." (PMID 23587053, 2013). "The lack of PALB2 methylation-positive samples in our study might be explained by the fact that we have investigated high-grade serous ovarian cancer cases only, which presumably evolve via a different tumorigenic pathway of development than clear cell carcinomas." (PMID 23587053, 2013).
pancreatic adenocarcinoma (7 papers, 2017 to 2025). "A Phase IB trial of the PARP inhibitor, veliparib, in combination with cisplatin and gemcitabine in patients with BRCA or PALB2-mutated pancreas adenocarcinoma reported 5 (56%) partial responses (PR), and 4 (44%) with stable disease in 9 patients who were BRCA-mutated." (PMID 29069866, 2017). "In a report of resected pancreatic adenocarcinoma, patients with germline BRCA1/BRCA2 and PALB2 mutations had better overall survival (OS) than patients without such mutations (median OS 46.6 months versus 23.2 months)." (PMID 36975505, 2023). "In the pancreatic adenocarcinoma cases of the project GENIE, which included 5262 cases profiled, the most prevalent oncogenic or likely oncogenic mutations in DDR-related genes were in ATM and in BRCA2, followed by lower frequencies in BRCA1, PALB2, ATR and BRIP1 and a few cases in other genes." (PMID 36975505, 2023).
ataxia telangiectasia (6 papers, 2013 to 2025). Ataxia-telangiectasia is the association of severe combined immunodeficiency (affecting mainly the humoral immune response) with progressive cerebellar ataxia. "Interestingly, our observations, which are consistent with deficient DNA DSB repair as a result of a defect in HR in these hypomorphic PALB2 patients, using the same endpoint show an effect greater than seen in classical ataxia telangiectasia patients." (PMID 26990772, 2016). "Seven of these patients were found to carry two pathogenic variants including one biallelic ATM carrier with a clinical diagnosis of ataxia-telangiectasia, two ATM/BRCA2 carriers, one BRIP1/BRCA2 carrier, one BRCA1/CHEK2 carrier, one BARD1/PALB2 carrier, and one CHEK2/PALB2 carrier." (PMID 28008555, 2017).
hereditary ovarian cancer (6 papers, 2015 to 2022). "Two-hit inactivation has also been described, in smaller case series, for PALB2- and ATM-related HBC, and BRIP1-related hereditary ovarian cancer." (PMID 32295625, 2020).
male breast carcinoma (5 papers, 2015 to 2023). A malignant neoplasm involving the male breast. "Notably, we found that CHEK2 and PALB2 were also associated with male breast cancer in GeneCards." (PMID 33959510, 2021). "Even though male breast cancer (MBC) risk encompasses both genetic and environmental aetiologies, the primary risk factor is a germline pathogenic variant (PV) or likely pathogenic variant (LPV) in BRCA2, BRCA1 and/or PALB2 genes." (PMID 37762649, 2023).
stomach cancers (5 papers, 2015 to 2025). "For case EI_1109, we identified a second relative with GC who carried the same PALB2 variant (Arg414Ter) and showed loss of heterozygosity (LOH) in her gastric tumour." (PMID 40446793, 2025).
acute myeloid leukemia (4 papers, 2021 to 2025). Acute myeloid leukemia (AML) is a group of neoplasms arising from precursor cells committed to the myeloid cell-line differentiation. "Whereas in acute myeloid leukemia, high expression of PALB2, on the contrary, was associated with worse OS parameters." (PMID 37628606, 2023).
bladder cancer (4 papers, 2014 to 2024). "A PALB2 mutation (509_510delGA) was present in four (0.3%) of 1413 cases with bladder cancer and in seven (0.15%) of 4702 controls (OR = 1.9; 95% CI 0.55–6.51; p = 0.5)." (PMID 33419454, 2021). "Thy found that frequency of gene PALB2 mutation was 1.49% in bladder cancer and 0% in kidney cancer tumors." (PMID 33419454, 2021). "In this study we found that mutations in PALB2 gene were seen in five (0.35%) unselected cases of bladder cancer and two (0.24%) unselected cases of kidney cancer." (PMID 33419454, 2021). "Among bladder cancer cases the PALB2 mutations (two variants combined) were found in 0.35% of the patients and in 0.21% of the controls (OR = 1.7; 95% CI 0.56–4.88; p = 0.52)." (PMID 33419454, 2021). "Bladder cancer cases and 4702 controls were successfully genotyped for the two PALB2 variants." (PMID 33419454, 2021). "Another report on 98 patients with bladder cancer showed that mutations in DNA repair genes (CHEK2, ERCC5, GEN1, MLH1, PALB2, RAD50, RAD51B and RECQL4) are associated with an unfavorable cancer prognosis and 22% of patients had a mutation." (PMID 35395863, 2022). "In 45 family cases with bladder cancer in first- and/or second-degree relatives we did not observed any of investigated mutations in gene PALB2." (PMID 33419454, 2021).
Cowden syndrome (4 papers, 2018 to 2025). "Currently, the NHS guidelines to the UK genetics departments allow estimation of BRCA1/2 and PALB2 (as well as syndromic genes where indicated such as PTEN in Cowden disease)." (PMID 33317064, 2020).
embryonal tumors (4 papers, 2016 to 2025). "In patients with FANCD1/BRCA2 or FANCN/PALB2 variants, additional screenings for embryonal tumors (e.g., brain MRI, abdominal ultrasound, and urine catecholamine) are recommended." (PMID 40970532, 2025). "Patients with biallelic PVs in FANCD1/BRCA2 and FANCN/PALB2 have very high risks of malignancies, and they can develop embryonal tumors which are not seen in patients with FA who have PVs in other FANC genes." (PMID 36091172, 2022). "It was, therefore, speculated that the mild clinical presentation of the disease in affected siblings, together with the absence of embryonal tumours, could be attributed to residual function of the exon 6 deletion mutant PALB2 protein." (PMID 26990772, 2016).
endometrial cancer (4 papers, 2015 to 2025). Primary or metastatic malignant neoplasm involving the endometrium (mucous membrane that lines the endometrial cavity). "Burden testing identifies 13 cancer genes with significant enrichment of rare truncations, some associated with specific cancers (for example, RAD51C, PALB2 and MSH6 in AML, stomach and endometrial cancers, respectively)." (PMID 26689913, 2015).
non-small cell lung carcinoma (4 papers, 2014 to 2023). A group of at least three distinct histological types of lung cancer, including non-small cell squamous cell carcinoma, adenocarcinoma, and large cell carcinoma. "There is also evidence that high expression of PALB2 in non-small cell lung cancer is associated with overall survival (at p = 0.0266)." (PMID 37628606, 2023). "PALB2 has been explored in the field of chemotherapy, and the presence of PALB2 mutation has been reported to be correlated with improved clinical outcomes in non-small cell lung cancer (NSCLC) treated with platinum-based chemotherapy." (PMID 35087742, 2021). "Interestingly, one recent Phase III clinical trial of non-small cell lung cancer demonstrated that patients with high PALB2 expression were more sensitive to cisplatin - docetaxel chemotherapy, suggesting PALB2 as a promising biomarker for the identification of chemotherapy-sensitive patients." (PMID 36158641, 2022). "However, the PALB2 characteristics, its correlation with immunotherapy biomarker, and the prognostic effect of immunotherapy in non-small cell lung cancer (NSCLC) were unknown." (PMID 35087742, 2021).
thyroid cancer (4 papers, 2018 to 2024). "Lastly, an affected woman with the PALB2 gene intronic variant, described relatives with ovary, breast, and thyroid cancers." (PMID 38890714, 2024).
desmoid tumor (3 papers, 2021 to 2024). A desmoid tumor (DT) is a benign, locally invasive soft tissue tumor associated with a high recurrence rate but with no metastatic potential. "In a small series of patients with desmoid tumors, disease-causing variants were identified in CHEK2, ERCC5, BLM, MSH6, and PALB2; however, none of these genes has been shown to be associated with increased risk of having desmoids." (PMID 38540414, 2024).